IFNG (interferon gamma)
Diseases named in the same sentence as IFNG in open-access papers (continued):
Sharing a sentence is not in itself a finding about the gene and the disease.
colitis (continued). "We have previously shown that a deficiency of CD1d-restricted invariant natural killer T (iNKT) cells exacerbates dextran sulfate sodium (DSS)-induced colitis in Yeti mice that exhibit IFNγ-mediated hyper-inflammation." (PMID 36499642, 2022). "Mice deficient in both IL-10 and IL-10R spontaneously develop colitis as IL-10 suppresses the inflammatory activity of various immune cells, and colitis in Il10−/− mice is mediated by Th1 cells and IFNγ." (PMID 33562334, 2021). "We confirm that the canonical JAK/STAT components of IFNG signaling are up-regulated in anti–CTLA-4/PD-1 colitis compared to controls." (PMID 34147519, 2021). "The knock-down of miR-155 protects the experimental colitis mice by decreasing IFNγ, TNFα, IL-6, IL-12 and IL-17 production, reducing Th1 response and suppressing the T-cells activation by DCs." (PMID 33921348, 2021). "It is worth noting that such an effect of RNPO was supported with decreased colitis disease index and pro-inflammatory cytokine interferon-gamma (IFN-γ)." (PMID 33540693, 2021). "In conclusion, our results provide evidence that iNKT cells contribute to protection against IFNγ-mediated colitis by cooperating with ILC3s." (PMID 33513946, 2021). "We have demonstrated by Nanostring and bulk RNASeq that IFNG signaling pathways are enriched in anti–CTLA-4/PD-1 colitis, but the source of IFNG message cannot be determined at a bulk RNASeq level." (PMID 34147519, 2021). "We have previously demonstrated that CD1d-dependent iNKT cells play a significant role in controlling DSS-induced colitis in C57BL/6 (B6) background Yeti mice with dysregulated IFNγ-mediated autoinflammation." (PMID 33513946, 2021). "Single-cell RNA sequencing analysis confirms activated CD8+ TRM cells express high levels of transcripts for checkpoint inhibitors and interferon-gamma in ICI-colitis." (PMID 34147519, 2021). "Analysis of cell types in the colon revealed that ILCs are the primary innate source of IFNγ in early onset of C. jejuni-mediated colitis." (PMID 34938670, 2021). "These components acted to protect mice against colitis inflammation by significantly suppressing cytokines [γ‐interferon (IFNγ), IL‐6,IL‐1β, and IL‐17a] related to colitis pathology and upregulating anti‐inflammatory cytokine IL‐10." (PMID 32410383, 2020). "Oral administration of berberine also ameliorates DSS-induced colitis and downregulates the expression of TNFα, IFNγ, KC, and IL-17 in colonic macrophages." (PMID 32855621, 2020). "More recently, a study has shown that inhibition of IFNγ results in disruption of the vascular barrier and inhibition of IFNγ ameliorates experimentally induced colitis in IFNγ knockout mice." (PMID 32635383, 2020). "Of note, the diminished population of IFNγ-expressing cells in the adoptive transfer colitis model was an unexpected observation, since we observed that activated NCOR1 cKOCd4 CD4+ T cells produced enhanced levels of IFNγ." (PMID 32318068, 2020). "Inflammation in this colitis model is driven by the recognition of gut flora by self-reactive T cells through the IL-23/IFNγ/IL-17 axis." (PMID 32639988, 2020). "A previous study showed that CD4+ T cells in IL-10-/- mice produced similar IFNγ levels compared to CD4+ T cells in IL-23-/-IL-10-/- mice in spontaneous model of colitis, indicating normal Th1 response in IL-23- and IL-10-deficient environment." (PMID 33488580, 2020). "IFNγ+ T cells in established TNBS-colitis mice were rich in CD81+ T cells at 3.7-fold (12.8% versus 3.5%) or 4.9-fold (6.4% versus 1.3%) compared with CD81− T cells with or without SEB stimulation, respectively." (PMID 32332834, 2020). "Elevated levels of TNF-α, IL-1β, and IFNγ due to activation of immune cells are hallmarks of colitis, in both humans and mice." (PMID 32377161, 2020). "Neutralizing of IFNγ prevents the development of severe C. jejuni-mediated colitis in IL-10-/- mice." (PMID 33488580, 2020).
colitis (continued). "In the TNBS mouse model of colitis, berberine reduces IFNγ, IL-1α, IL-6, IL-17, and TNFα expression in colonic tissues and sera and suppresses Th1 and Th17 cells through reduction of STAT1, STAT3, and NF-κB phosphorylation." (PMID 32855621, 2020). "The algae alkaloid caulerpin reduces DSS colitis by suppressing NF-κB activation and subsequently inhibiting the colonic production of TNFα, IFNγ, IL-6, IFNγ, and IL-17." (PMID 32855621, 2020). "Our results suggest that IL-23 promotes pathogenesis of C. jejuni-induced colitis by recruiting myeloid cell populations in the colon and enhancing IL-17 and IFNγ responses by group 1 and 3 innate lymphoid cells." (PMID 33488580, 2020). "Instead of IFNγ- and IL-17-mediated colitis, these mice developed a type 2 intestinal immune response that prevented the deleterious effects of an aberrant activation of the immune system." (PMID 30356098, 2019). "Starting from the observation that Tregs isolated from the lamina propria of active but not inactive IBD patients or uninflamed controls express Tbet and IFNγ, we investigated the functional role of Th1-like Tregs in the dextran sulfate model of colitis." (PMID 31572375, 2019). "In contrast, colitis development in Il10−/− mice is driven by an aberrant response of Th1 cells and exaggerated production of pro-inflammatory cytokines such as IFNγ, IL17, and IL12 to microbiota-derived antigens." (PMID 31396223, 2019). "Intraepithelial ILC1s and IFNγ-producing ILC3s accumulated in mice, and blocking IFNγ ameliorated intestinal inflammation in a mouse model of colitis." (PMID 31134022, 2019). "Taken together, these data indicate that in a colitis model characterized by the alteration of the epithelial barrier, Tregs acquire a Th1-like phenotype characterized by Tbet and IFNγ expression." (PMID 31572375, 2019). "Remarkably increased IFNγ was detected not only in DSS-mediated colitis but also in E.coli O160:H7 colonized colon tissues as compared with their control mice, whereas other anti-inflammatory cytokines such as IL-4 did not significantly change." (PMID 31707260, 2019). "T-cells are key cells of the adaptive immune system and have important effector functions in colitis through production of IFNγ." (PMID 30936879, 2019). "In this this context, Th1-like Tregs would represent an another source of IFNγ-producing cells involved in colitis development." (PMID 31572375, 2019). "We also demonstrate that mice developing chemically-induced colitis are characterized by an increased number of IFNγ-expressing Th1-like Tregs in the intestinal lamina propria and that their upregulation precedes the accumulation of conventional Th1 cells." (PMID 31572375, 2019). "In conclusion, we clearly reveal a distinct role of IFNγ for the development of intestinal inflammation in two different mouse models of colitis in the same mouse strain with the same microbial composition." (PMID 29416538, 2018). "This suggests that ILC3 intrinsic IFNγ-production was sufficient for induction of acute intestinal inflammation in the anti-CD40 innate colitis model." (PMID 29416538, 2018). "Next, we investigated the cell types that contribute to disease pathogenesis in DSS-induced colitis under IFNγ dysregulated conditions." (PMID 30333822, 2018). "In a mouse model of T cell-induced colitis, GM-CSF increased the production of IL-4, IL-10, and IL-13 and decreased the production of interferon gamma (IFN-γ) in lamina propria mononuclear cells." (PMID 29703251, 2018). "Hemizigosity in EP4 during T cell induced colitis in the adoptive T cell transfer colitis model is partially protective, and also affects IFNγ and IL2 production by MLN CD4+ cells." (PMID 30619314, 2018). "ODNs given therapeutically after colitis has developed worsen disease whereas when given prophylactically there is a reduction in inflammation thought possible due to a tolerance effects on IFNγ or on increasing IL-10 production." (PMID 29515999, 2018).
colitis (continued). "To specifically address these issues, we aimed to investigate the role of IFNγ in two frequently used models of colitis (innate vs. adaptive immune driven colitis models), using genetically and microbiota-stabilized hosts." (PMID 29416538, 2018). "Co-transfer of Treg cells prevented colitis by reducing the expansion of activated IFNγ-producing and IL-17-producing CD4+ T cells." (PMID 29549257, 2018). "In the present study, we strengthen the observations of the differential role of IFNγ during innate vs. adaptive murine models of colitis." (PMID 29416538, 2018). "On the other hand, protective effects of IL17A were ascribed to an IL17A-mediated attenuation of T-bet and IFNγ expression, leading to a more aggressive colitis upon transfer of IL17A−/− CD4 T cells into lymphopenic hosts." (PMID 29416538, 2018). "Nonetheless, contradictory results concerning the relevance and source of IFNγ in the development of colitis have also been reported." (PMID 29416538, 2018). "Here, we have investigated the role of iNKT cells in colitis induced by DSS in Yeti mice with dysregulated IFNγ-mediated intestinal inflammation." (PMID 30333822, 2018). "The inability to ameliorate colitis by inhibiting IFNγ has been attributed to the emergence of pro-inflammatory Th17 cells." (PMID 29416538, 2018). "Taken together, we demonstrate that depending on the mode of colitis induction, IFNγ is critical for disease induction in the innate anti-CD40 mediated colitis model, whereas IFNγ production is dispensable in the CD4 T cell-dependent transfer colitis." (PMID 29416538, 2018). "In a similar TNBS-colitis study, rCTB administration reduced IL-12 and IFNγ secretion, inhibited STAT-4 and STAT-1 activation, and downregulated T-bet expression, indicating that rCTB inhibited mucosal Th1 cell signaling." (PMID 29168738, 2017). "In this context, it is relevant that TNBS colitis can be treated with antibodies to IL-12, one of the key inducers of IFNγ." (PMID 29312281, 2017). "First we confirmed our results by showing that IL-17A (Th17) and IFNγ (Th1) are decreased in MLN from LL-pILMAM group in DNBS-induced colitis." (PMID 28203226, 2017). "The colitis mice given a neutralizing S100a9 antibody produced less inflammatory cytokines, such as Tnfα, Il1β, Il6, Il17a, Ifnγ, and Il12a, all of them are master regulators of inflammation and tumorigenesis." (PMID 29326691, 2017). "PLP treatment ameliorated colitis in IL-10−/− mice due to a reduction in colonic TNFα, IL-6, IFNγ, COX-2 and nitric oxide synthase (iNOS) expression and modulation of the chemotactic lipid S1P." (PMID 28804483, 2017). "Nuclear factor-kB participates in controlling the activation of various pro-inflammatory cytokine genes such as IL6, IFNγ or IL17 suggesting that NF-κB pathway is also turned off in MAM treated mice in DSS colitis model." (PMID 28203226, 2017). "Similar to CD, mouse models of experimental colitis trigger a Th1 type immune response, reflected by the infiltration of IFNγ-producing T cells in the colon." (PMID 28484453, 2017). "IL23 responsive ILC have been implicated in the pathogenesis of colitis in several innate murine models through the production of IL17, IFNγ, and GM-CSF." (PMID 29081776, 2017). "Compared to the control, Th1 cell populations (CD4+IFNγ+) and Th17 subsets (CD4+IL-17A+) increased in the spleen, MLN and colon tissues of mice with colitis as well as the enhanced concentrations of IFNγ and IL-17 in colon homogenate supernatants." (PMID 26728323, 2016). "This is in contrast to the important role of IFNγ during other bacterial gut infections as well as in later stages of S.Tm infection, where pathogen resistance, colitis and systemic pathogen restriction are coupled to a functional IFNγ response." (PMID 27341123, 2016). "We show thatthe gene expression of IFNγ and iNOS was attenuated in the colon ofgp130757F/F LysMcre/STAT3flox mice with acuteDSS-induced colitis." (PMID 26848037, 2016).
colitis (continued). "Most importantly, NHE3 expression and/or activity are depressed in vitro by IFNγ, in vivo in several models of experimental colitis, and in IBD patients." (PMID 27050757, 2016). "The DSS colitis model has been characterized by increased serum levels of IL-6, IL-17, and TNFα and elevated levels of IL-4, IL-6, IL-10 and IFNγ have been reported in chronic colitis." (PMID 27177331, 2016). "Taken together, these observations, particularly the elevated expression of the helper T cells (Th)-related cytokines IFNγ and IL-17, suggested the involvement of Th cells in colitis in Lck-cre:TAK1fl/fl mice." (PMID 26132627, 2015). "Another study suggested that RELM-β promotes the chronicity of T. muris infections as well as the severity of colitis by increasing IFNγ production by CD4+ T cells." (PMID 26285214, 2015). "In contrast, IL-22 expressers from colitic mice, transferred into secondary hosts, lost reporter expression, acquired high T-bet and modest IFNγ and IL-17 expression, and induced severe colitis." (PMID 26834739, 2015). "DSS-induced colitis, on its own, significantly increased the mRNA expression of Ifnγ, Il6, Il17 and Tgfβ as compared to controls." (PMID 24787575, 2014). "TNBS-induced colonic inflammation in mice is a commonly used chemically induced model that features up-regulation of pro-inflammatory cytokines (IL-1β, IFNγ, TNFα, IL-12, IL-17A)." (PMID 22461841, 2012). "Probiotic administration attenuated development of signs and symptoms of colitis, reduced colonic expression of TNFα, IL-6 and IFNγ and reserved colonic downregulation of PPARγ, PXR and FXR caused by TNBS." (PMID 21829567, 2011). "IFNγ blockade, or low-dose penicillin to target Gram-positive bacteria, in early life impaired microbiome-mediated epigenetic control and mucosal immunity, and exacerbated colitis." (PMID 41857413, 2026). "This suggests that IL-36γ drives IFNγ-dependent T cell mediated colitis." (PMID 40642091, 2025). "Additionally, AhR∆IEC colitis mice showed significantly higher levels of mRNA expression of proinflammatory cytokines IL‐1β, IFNγ, and TNFα in colonic mucosa when compared to WT mice with colitis." (PMID 40410944, 2025). "IFNγ is largely produced by innate lymphoid cells (ILCs), NK cells, and activated T cells, and is elevated in the mucosa of patients with Crohn’s disease along with animal models of colitis." (PMID 41425579, 2025). "Given that IL-18 is found in elevated levels in UC patients, a study that used wild type (WT), IL-18-/-, and IL-18R-/- mice in DSS colitis model found that IFNγ production and IL-17 producing CD4+ T cells were reduced in the colons of both knockout models, along with less severe colitis than WT." (PMID 40642091, 2025). "Additionally, anti‐CD40‐induced colitis mice showed significantly higher levels of mRNA expression of proinflammatory cytokines IL‐1β, IFNγ, and TNFα in colonic mucosa when compared to controls." (PMID 40410944, 2025). "Findings from selective depletion of CD4+ and CD8+ T cells or the use of IFNγ‐neutralizing antibodies in ICB‐driven colitis indicated that CD4+ T‐cell‐mediated responses and IFNγ are primarily responsible for the intestinal inflammation caused by CTLA‐4 blockade." (PMID 38881673, 2024). "Moreover, we have found that ILC1 are a significant driver for the development of DSS-induced colitis and early IFNγ production is likely to be key in the induction of colitis by ILC152." (PMID 39496592, 2024). "Furthermore, it has been reported that EP4 signaling mitigates TNBS-induced colitis and reduces colonic mRNA expression of colitogenic cytokines, including IFNg." (PMID 39596393, 2024). "To investigate the role of mPGES-1 in the development of Th17/Th1 immune responses involved in colitis, we next analyzed the proportions of Th17 and Th1 cells that produced IL-17A and IFNγ in mesenteric lymph nodes (MLNs) of mPGES-1−/− and WT mice following colitis induction." (PMID 39596393, 2024).
colitis (continued). "In CPI colitis, IFNγ producing lymphocytes also upregulated co-inhibitory receptors." (PMID 37872166, 2023). "Seven hub genes IL10, IL4, IL6, IFNG, IL1B, TNF and IL17A might be responsible for causing Colitis and Arthritis, except for Rheumatoid Arthritis." (PMID 36989283, 2023). "Crucially, we identify the IL23 and IFNγ as a functionally important cytokine axis in CPI colitis." (PMID 37872166, 2023). "IFNγ and/or IL-17 A production by T cells is necessary for colitis development." (PMID 38012544, 2023). "In the acute TNBS-induced colitis model, IFNγ-producing Th1 cells dominate the pathology, while Th17 cells are also involved and may have both an effector and a regulatory role (reviewed in ref.20)." (PMID 36690619, 2023). "This pre-clinical model of CPI-colitis could be attenuated following blockade of the IL23/IFNγ axis." (PMID 37872166, 2023). "Similarly, treatment with phages have been also shown to trigger immune cell expansion with the stimulation of interferon gamma, exacerbated gut inflammation in a mouse model of colitis." (PMID 36466675, 2022). "Additionally, the effect of MDA resembles the anti-inflammatory effects induced by the A. adstringens extract when tested in a colitis model as it decreased the levels of cytokines such as TNFα and IFNγ and it also restricted tissue damage." (PMID 35209237, 2022). "Although IFNγ-producing CD8+ TRM cells are a pathological hallmark of immune checkpoint inhibitor treatment related colitis, we did not observe the expansion and activation of CD8+ TRM cells in DSS-induced colitis." (PMID 35844584, 2022). "CD4+ T cell–derived cytokines such as IL-17A and IFNγ are pro-inflammatory and have been shown to be pathogenic in murine models and in patients with IBD, whereas Treg cells protect mice from DSS-induced colitis." (PMID 35844584, 2022). "In heterozygous Yeti mice, high levels of IFNγ can increase the number of cytotoxic CD8+ T cells expressing NK cell receptors (i.e., NK1.1 and NKG2D), resulting in increased susceptibility to dextran sulfate sodium (DSS)-induced colitis." (PMID 36499642, 2022). "From a therapeutic stance, IP in particular has shown potential in a murine model of colitis where administration of the ketoacid not only improved disease outcome, but also decreased expression of pro-inflammatory cytokines, including IL-12, IFNγ, and TNF." (PMID 35052669, 2022). "Here, IL-17A and IFNγ production was strongly increased in CD4+ T cells from mice with colitis." (PMID 35844584, 2022). "IFNγ levels in T cells from control PTENΔDC mice were up to 2-fold elevated and IFNγ KO mice are protected from colitis induction, highlighting the pivotal role of Th1 mediated responses in the pathogenesis of colitis, which is to some extent driven by PI3K signaling in dendritic cells." (PMID 35514976, 2022). "Despite a strong association of IFNγ with murine models of colitis, the clinical response of fontolizumab, a humanized anti-IFNγ specific antibody, in IBD patients was not detectable although improved inflammatory scores were observed." (PMID 34795671, 2021). "In addition, we revealed that the mRNA levels of IL-2 and IFNγ were mitigated by the oral administration of THF in a colitis model." (PMID 33669855, 2021). "The pro-inflammatory cytokine interferon-gamma (IFNγ) plays a critical role in DSS-induced colitis." (PMID 33513946, 2021). "In support of the possibility that colitis-associated inflammatory factors contribute to neuroinflammation, we observed increased plasma concentrations of TNFα, MCP-1/CCL2, IL-6, and IFNγ in colitic mice, as well as increased transcription of Tnf, Il1b, and Il6 in their brains." (PMID 34511110, 2021). "Furthermore, IFNγ appears to be the most critical factor driving colitis, while IL-17A and IL-13 play a less important role." (PMID 34795671, 2021).